ZNF260 (zinc finger protein 260)
Description:
Transcription factor that acts as a cardiac regulator and an effector of alpha1-adrenergic signaling. Binds to PE response elements (PERE) present in the promoter of genes such as ANF/NPPA and acts as a direct transcriptional activator of NPPA. Also acts as a cofactor with GATA4, a key cardiac regulator (By similarity).
Synonyms: ZFP260; ozrf1
Tractability: PROTAC: ubiquitination databases record sites on it.
Gene: Protein-coding gene on chromosome 19 (36,510,687 to 36,528,696, reverse strand). Ensembl gene ENSG00000254004.
Subcellular location: Nucleus
Subcellular location (Human Protein Atlas): Cytosol; Nucleoplasm
Gene Ontology:
Molecular function: protein binding; DNA-binding transcription factor activity, RNA polymerase II-specific; RNA polymerase II cis-regulatory region sequence-specific DNA binding
Biological process: regulation of transcription by RNA polymerase II
Cellular component: nucleoplasm; nucleus
Genetic constraint (gnomAD): Loss-of-function variants: 21 observed, 31.3 expected, observed/expected ratio (o/e) 0.67, 90% interval 0.47 to 0.97. The upper end of that interval is the gene's LOEUF score, 0.97, which puts it in group 4 of 6, group 1 being the genes least tolerant of losing a copy. Missense variants: 465 observed, 516.01 expected, observed/expected ratio (o/e) 0.9, 90% interval 0.83 to 0.97. Synonymous variants: 156 observed, 166.95 expected, observed/expected ratio (o/e) 0.93, 90% interval 0.82 to 1.07.
Homologues: Orthologues: chimpanzee ZNF260 (100% identical), macaque ZNF260 (98% identical), dog ZNF260 (93% identical), rabbit ZNF260 (92% identical), pig ZNF260 (92% identical), guinea pig ZNF260 (88% identical), mouse Zfp260 (86% identical), rat Zfp260 (85% identical). Paralogues in human: ZNF182 (57% identical), ZNF146 (57% identical), ZNF568 (57% identical), ZNF33B (56% identical), ZNF484 (56% identical), ZNF658 (56% identical), ZNF605 (55% identical), ZNF717 (55% identical), ZNF28 (54% identical), ZNF41 (54% identical), ZNF16 (54% identical), ZNF534 (54% identical), and 164 more.
Diseases named in the same sentence as ZNF260 in open-access papers:
ZNF260 is named in the same sentence as 2 diseases in open-access papers, as found by Europe PMC text mining. Sharing a sentence is not in itself a finding about the gene and the disease. The quoted sentences say what the papers report.
cardiac hypertrophy (1 paper, 2023). "Zinc finger protein 260 (Zfp260), also known as phenylephrine-induced complex-1 (PEX1), is an effector of α-1-adrenergic signaling in cardiac hypertrophy." (PMID 38143497, 2023).
ZNF260 also shares sentences with these, for which no sentence is quoted: Sepsis (1 paper).